PLIN2 (perilipin 2)
Diseases named in the same sentence as PLIN2 in open-access papers (continued):
Sharing a sentence is not in itself a finding about the gene and the disease.
Alzheimer disease (5 papers, 2017 to 2025). A progressive, neurodegenerative disease characterized by loss of function and death of nerve cells in several areas of the brain leading to loss of cognitive function such as memory and language. "LACTB2 and PLIN2 had novel significant associations with Alzheimer’s disease and BIN1, PTK2B, SPI1, MS4A4A, MS4A6E, APOE and PVR are in known Alzheimer’s disease risk loci from GWAS." (PMID 33959712, 2021). "As immunity is important in Alzheimer’s disease, this provides a biological interpretation in immune cells, of genome-wide association studies and implicates two novel genes, PLIN2 and LACTB2, in Alzheimer’s disease." (PMID 33959712, 2021). "Three of these genes: STX3, LACTB2 and PLIN2 had novel significant associations with Alzheimer’s disease." (PMID 33959712, 2021). "The association between a decrease in expression of PLIN2 and Alzheimer’s disease was detected exclusively in LPS2 induced monocytes." (PMID 33959712, 2021). "We discovered age-dependent genetic effects, established associations between vascular-related genes (KLKB1, F12, PLIN2) and midlife plasma aβ levels, and identified a plausible Alzheimer’s Disease candidate gene (ITPRIP) influencing cell death." (PMID 28704393, 2017). "Our analysis identified two novel candidate genes for Alzheimer’s disease risk, LACTB2 and PLIN2/ADRP." (PMID 33959712, 2021). "Moreover, single nucleus RNA-seq data from the Seattle Alzheimer’s Disease Brain Cell Atlas (SEA-AD) showed enriched levels of PLIN2 in the microglia cluster, particularly among 24 individual clusters based on the cell types in AD brain." (PMID 37626048, 2023). "We also detected TWAS signals in two genes, LACTB2 and PLIN2 that have not been associated with Alzheimer’s disease previously." (PMID 33959712, 2021). "Finally, a recent expression study on all human perlipin proteins (PLIN1-5), found that PLIN2 accumulates, particularly in neurons, in brains of old subjects and of patients with Alzheimer disease." (PMID 34788284, 2021).
Hyperglycemia (5 papers, 2017 to 2021). An increased concentration of glucose in the blood. "It is plausible that the loss of PLIN2 in β cells confers protection under severe ER stress and extreme hyperglycemia, as seen in Akita mice." (PMID 33784258, 2021). "Up‐regulation of PLIN2 in T2D patients is likely caused by a combination of hyperglycaemia, hyperlipidaemia, inflammation and oxidative stress, among others." (PMID 30710421, 2019). "Collectively, these data indicate that the loss of PLIN2 partially rescues the insulin deficiency and hyperglycemia of Akita mice." (PMID 28102311, 2017). "In our study, the ablation of Plin2 in Akita mice partially reverses hyperglycemia and insulin deficiency." (PMID 28102311, 2017). "Consistent with human tissue, both LD formation and PLIN2 expression were enhanced in INS‐1 cells under hyperglycaemia, whereas TFEB activation and autophagy gene expression were significantly reduced." (PMID 30710421, 2019). "Genetic ablation of Plin2 in Akita mice led to significant amelioration of hyperglycemia, decreased β cell apoptosis, and partially restored β cell mass and pancreatic insulin content." (PMID 28102311, 2017). "After acute exercise, the expression of Plin2 was decreased significantly, which might lead to an improvement in insulin sensitivity and hyperglycemia in the exercised GK rats." (PMID 31579613, 2019). "Interestingly, FA treatment under hyperglycaemia lowered the effect of hyperglycaemia on Plin2 expression." (PMID 30710421, 2019). "In addition, we show that hyperglycaemia alone was the main factor leading to significant up‐regulation of Plin2 (P < 0.001), while FA alone (normoglycaemic conditions) only slightly elevated Plin2 mRNA." (PMID 30710421, 2019). "Based on previous studies, we found the dysregulations of Plin2, Alox15, Nr1i2, and Nr1d1 genes related to lipid metabolism might implicate to the disorders of the hypothalamus in the diabetic GK rats and contribute to the hyperglycemia in them." (PMID 31579613, 2019). "Nevertheless, our data clearly indicate that the reduction of PLIN2 in β cells does not confer any protection against development of the modest hyperglycemia observed in mice on HFD." (PMID 33784258, 2021). "Thus, the reduction of PLIN2 in mouse β cells blunts GSIS in vivo, but likely to an extent not severe enough to cause overt hyperglycemia in βKO mice fed HFD." (PMID 33784258, 2021).
lung carcinoma (5 papers, 2022 to 2025). "In lung cancer, the high expression of PLIN2 indicates poor prognosis." (PMID 37998612, 2023). "The expression of PLIN2 protein does not correlate well with the mRNA level, suggesting that translational or post-translational regulation may be involved in the PLIN2 expression in lung cancer cells." (PMID 36293388, 2022). "It has been demonstrated previously that the other hub mRNAs (PBX1, PLIN2, and TPSAB1) are closely related to the progression of lung cancer and COPD by regulating the cell cycle and cell proliferation." (PMID 39940682, 2025). "The expression levels of PLIN2 and PLIN3 tend to be higher in lung cancer cell lines than normal ones, and the levels of PLIN3 better recapitulate the amount of LD than the levels of PLIN2, except for the high PLIN3 expression in a low LD cell line, WI-38 cells." (PMID 36293388, 2022).
melanoma (5 papers, 2021 to 2025). A malignant, usually aggressive tumor composed of atypical, neoplastic melanocytes. "For example, the key lipid droplet protein DGAT1 promotes melanoma growth, and our data using the Plin2 lipid droplet reporter suggest that this is likely increased in the Agrp animals." (PMID 36472402, 2023). "Similarly, we expressed the PLIN2-tdTOMATO transgene in melanoma cells and found that the nitric oxide pathway also regulated lipid droplets in cancer." (PMID 34114952, 2021).
nonalcoholic steatohepatitis (5 papers, 2014 to 2022). "In the liver, Perilipin 2 (Plin2) is the most abundant lipid droplet protein; while Perilipin 3 (Plin3) is mildly expressed and Perilipin 1 (Plin1) is de novo expressed in non-alcoholic steatohepatitis." (PMID 24831094, 2014). "Additionally, the majority of the mentioned studies assessed PLIN2 in NAFLD or non-alcoholic steatohepatitis (NASH) instead of cirrhosis, further reducing the comparability of the results." (PMID 34572396, 2021). "Interestingly, the liver biopsies from nonalcoholic steatohepatitis patients show increased levels of PLIN2 in lipid droplets, indicating the importance of Plin2 for individuals with NAFLD." (PMID 26935102, 2016).
colon adenocarcinoma (4 papers, 2018 to 2025). "We also suggest the use of lipid droplets and their associated structural protein PLIN2 as tumor biomarkers for colon adenocarcinoma." (PMID 30782775, 2019). "Furthermore, positive PLIN2 staining was strongly associated with highly proliferative Ki-67-positive areas in human colon adenocarcinoma tissue samples." (PMID 30782775, 2019). "PLIN2 accumulation is associated with highly proliferative human colon adenocarcinoma tissues." (PMID 30782775, 2019). "The pattern of PLIN2 staining observed in EAC samples was similar to that of colon adenocarcinoma samples, used as positive control." (PMID 33441691, 2021). "Following this reasoning, we evaluated the presence and pattern of PLIN2 protein by immunohistochemistry, as a marker of lipid droplet accumulation in samples of human colon adenocarcinoma tissues and in paired adjacent normal tissues." (PMID 30782775, 2019). "Nevertheless, PLIN2 appears to be an interesting biomarker for highly proliferative colon adenocarcinoma, distinguishing cancerous tissue from normal tissue in paired samples from the same patient to an exceptional degree." (PMID 30782775, 2019). "Collectively, these data highlight PLIN2 protein as a potential biomarker for highly proliferative human colon adenocarcinoma." (PMID 30782775, 2019).
colon cancer (4 papers, 2018 to 2023). "Affected tissue of IBD and colon cancer patients, colonic and infiltrated immune cells, have increased LDs’ coat protein, PLIN2." (PMID 37298680, 2023). "To determine the significance of increased LDs in human intestinal pathobiology, we assessed the levels of PLIN2, the LDs coat protein, in affected tissue obtained from UC and CD patients and in tumor tissue from colon cancer patients." (PMID 37298680, 2023). "Similar increased PLIN2 levels were found in human colonic tumor tissue (adenocarcinoma, Stage IIB, and Stage IIIC) relative to adjacent normal tissue." (PMID 37298680, 2023). "In colon cancer, PLIN2 supported LD formation upon FOX and 5-Fu treatments; LD accumulation could consequently avoid PD-L1 and PD-1 exposure to tumor and CD8+T cells, respectively, thus leading to immunotherapy failure in addition to FOX resistance." (PMID 35372038, 2022). "Finally, by analyzing the border region between the colon tumor and the normal tissue, it is possible to clearly point out the significant difference in PLIN2 positivity observed in the tumor tissue (center)." (PMID 30782775, 2019). "Finally, we determined the expression pattern of PLIN2 protein in highly proliferative human colon cancer tissues." (PMID 30782775, 2019).
Glucose intolerance (4 papers, 2014 to 2025). Glucose intolerance (GI) can be defined as dysglycemia that comprises both prediabetes and diabetes. "Our future studies will investigate specific mechanisms by which Plin2 deficiency protects against pancreatic beta cell dysfunction and glucose intolerance." (PMID 24831094, 2014). "We previously reported glucose intolerance develops in alcohol-fed WT mice at four weeks of feeding and coincides with an upregulation of hepatic Plin2." (PMID 24831094, 2014). "While we did not directly test insulin sensitivity here, our findings suggest improvement of hepatic insulin sensitivity, since absence of Plin2 prevents alcohol-induced glucose intolerance and restores glycogen stores (data not shown) to levels of control-fed WT mice." (PMID 24831094, 2014).
Granuloma (4 papers, 2016 to 2025). A compact, organized collection of mature mononuclear phagocytes, which may be but is not necessarily accompanied by accessory features such as necrosis. "Furthermore, we identified Flrt2, Hyal1, and Mmp13 as novel molecular markers of Plin2-expressing macrophages, which were localized to the peripheral rim regions of necrotizing granulomas." (PMID 40843005, 2025). "In non-necrotic granulomas at 8 weeks p.i., localization of MSR1 or LGALS3 was consistent with that of PLIN2, suggesting that these two proteins are also the marker for FM in non-necrotic granulomas." (PMID 36237431, 2022). "In non-necrotic granulomas, ARG1+ cells were distinct from PLIN2+ cells." (PMID 36237431, 2022).
hyperlipidemia (4 papers, 2016 to 2024). "Because the increased presence of lipid droplets and the increased expression of perilipin-2 may in theory be related to the hyperlipidemia common in patients with NS, we evaluated plasma lipid spectra." (PMID 36613637, 2022).
lipid metabolism disorders (4 papers, 2022 to 2026). "To explore whether tumor cells have lipid metabolism disorders after being co-cultured with M0-SNX10-EO macrophages, we evaluated PLIN2 mRNA levels in the ovarian cancer cells A2780 and A2780/CP70 and observed significant upregulation in both cell lines." (PMID 40426851, 2025).
liver disease (4 papers, 2016 to 2024). "Therefore, we next investigated whether changes in serum PLIN2 were associated with the presence of various comorbidities: (a) cardiovascular disease, (b) hepatic disease, (c) pancreatic disease, and (d) malignant disease." (PMID 34572396, 2021). "Prompted by experimental research connecting changes in PLIN2 serum levels with hepatic diseases and alcohol consumption, we analyzed serum PLIN2 concentrations in ICU patients suffering from liver cirrhosis and patients with a history of alcohol abuse." (PMID 34572396, 2021). "By contrast, increased levels of perilipin-2, amyloid A-1, and interferon (IFN)-γ signalling pathway-related proteins were observed in the livers of infected pregnant mice, suggesting that IFN-γ signalling may contribute to the development of liver disease during malaria in pregnancy." (PMID 34906158, 2021).
non-alcoholic fatty liver disease (4 papers, 2016 to 2025). "These proteins were mainly involved in fatty acid metabolism (Fasn, Scd1, Fads2, Fdps, Plin2), fatty acid degradation (Ehhadh, Acsl1), PPAR signaling pathway (Fads2, Ehhadh, Acsl1, Fabp1), non-alcoholic fatty liver disease (Ehhadh, Pklr) and AMPK signaling pathway (Fasn, Scd1, Hnf4a)." (PMID 32210812, 2020).
ovarian carcinoma (4 papers, 2017 to 2025). A malignant neoplasm originating from the surface ovarian epithelium. "The results demonstrated that the migration and invasion of ovarian cancer cells were enhanced by macrophages overexpressing PLIN2." (PMID 39921309, 2025). "This study interrogated the single‐cell transcriptome of immune cells across multiple anatomical sites in ovarian cancer patients and identified a novel subset of macrophages that are enriched in ascites and overexpressed the lipid droplet protein PLIN2." (PMID 39921309, 2025). "Since SNX10 causes macrophage lipid metabolism dysfunction, in order to explore whether it also affects the lipid content in ovarian cancer cells, the lipid droplet coating protein (PLIN2) mRNA expression in tumor cells was investigated." (PMID 40426851, 2025). "Searching the Kaplan–Meier Plotter database, it was found that PLIN2 was negatively correlated with PFS and OS in ovarian cancer." (PMID 40426851, 2025). "Firstly, we ectopically overexpressed PLIN2 in THP‐1‐derived macrophages and subsequently incubated the conditioned medium from these cells with human ovarian cancer cells SK‐OV‐3 and OVCAR‐3." (PMID 39921309, 2025). "PLIN2 expression had a negative correlation with ovarian cancer prognosis as assessed by the Kaplan–Meier Plotter database." (PMID 40426851, 2025).
renal carcinoma (4 papers, 2021 to 2022). A carcinoma arising from the epithelium of the renal parenchyma or the renal pelvis. "In contrast, other studies concluded that suppression of PLIN2 promoted cell proliferation, invasion, and migration in uterine leiomyoma and renal cancer." (PMID 35372038, 2022). "Moreover, we proved that two lipid regulatory genes HILPDA and PLIN2, important for ferroptosis sensitization in renal cancers, were significantly upregulated following RXD treatment and the upregulation was merely HIF-2α-dependent." (PMID 36209275, 2022). "NNMT, PLOD2, HAPLN3, PLIN2, and SLC16A3 showed medium to strong tumor-specific staining in more than 90% renal cancer samples, indicating higher general applicability of these biomarkers." (PMID 35440542, 2022).
Stroke (4 papers, 2023 to 2025). Sudden impairment of blood flow to a part of the brain due to occlusion or rupture of an artery to the brain. "Specifically, PPARα KO led to increased expression levels of Gadd45b, Nppa, Hdc, Lcn2, Il6, Sox4, Marcksl1, Saa3, Ucn2, Met, Dusp10, Elovl7, Ngf, C3, Il11, Hmox1, Alox5, Tnfsf9, Angptl4, Plin2, H19, Csf2rb, Atf3, and Col7a1 following stroke." (PMID 40362325, 2025). "Hence, microglia display enhanced levels of LD accumulation and elevated perilipin 2 (PLIN2) expression patterns when exposed to hypoxia or stroke." (PMID 39252446, 2024). "Stroke increased the mRNA expression of PLIN2 and ISG15, one of the typical type I IFN responsive genes, suggesting that the molecular machinery related to lipid droplet biogenesis was activated after stroke in the human brain too." (PMID 36541061, 2023).
Burkitt lymphoma (3 papers, 2012 to 2025). A rare form of malignant mature B-cell non-Hodgkin lymphoma. "In Burkitt lymphoma, PLIN2 was mainly expressed in immature B lymphocytes." (PMID 35372038, 2022).
Cirrhosis (3 papers, 2021 to 2024). A chronic disorder of the liver in which liver tissue becomes scarred and is partially replaced by regenerative nodules and fibrotic tissue resulting in loss of liver function. "However, we did not observe any connections between cirrhosis or alcohol abuse and PLIN2 levels." (PMID 34572396, 2021).
COVID-19 (3 papers, 2021 to 2024). A disease caused by infection with severe acute respiratory syndrome coronavirus 2. "Seven lipophagy-related genes, including ACADVL, HYOU1, DAP, AUP1, PRXAB2, LSS, and PLIN2, were used as biomarkers and drug targets for COVID-19." (PMID 38932215, 2024). "Lastly, a recent study involving machine learning algorithms identified seven lipophagy-related biomarkers for COVID-19, with one gene called PLIN2." (PMID 39308871, 2024). "In this study, we observed that PLIN2 expression levels were upregulated in the BALF of COVID-19 patients and the lungs of deceased patients." (PMID 38932215, 2024). "In sum, this study identifies seven lipophagy-related genes (ACADVL, HYOU1, DAP, AUP1, PRXAB2, LSS, and PLIN2) as biomarkers and potential therapeutic targets for COVID-19." (PMID 38932215, 2024). "The lipophagy-related genes ACADVL, HYOU1, DAP, AUP1, PRXAB2, LSS, and PLIN2 can be used as biomarkers and drug targets for COVID-19." (PMID 38932215, 2024). "In the validation set (GSE190496), we observed a significant increase in the gene expression levels of LSS, HYOU1, ACADVL, PRKAB2, PLIN2, AUP1, and DAP in the COVID-19 group compared to the control group." (PMID 38932215, 2024).
leiomyoma (3 papers, 2012 to 2026). A well-circumscribed benign smooth muscle neoplasm characterized by the presence of spindle cells with cigar-shaped nuclei, interlacing fascicles, and a whorled pattern. "In contrast, leiomyoma cultures exhibited widespread CD24/CD73 expression, focal CD49b clusters, high Ki67 positivity, metabolic reprogramming toward complex carbohydrate degradation, SLC-mediated transport, and a low-PLIN2/high-ACLY signature." (PMID 42099382, 2026).
liposarcoma (3 papers, 2020 to 2023). A usually painless malignant tumor that arises from adipose tissue. "In dedifferentiated sarcomas, pleomorphic liposarcomas, and other high-grade sarcomas, PLIN2 was more distinctly positive, suggesting its potential as a therapeutic target." (PMID 37998612, 2023). "The expression rates of PLIN1 (P<0.001), PLIN2 (P=0.034), and PLIN4 (P<0.001) were significantly different in subtypes of liposarcoma, while the expression rates of PLIN3 (P=0.25) and PLIN5 (P=0.051) were not significantly different." (PMID 32368290, 2020). "The expression levels of PLIN1 (P<0.001), PLIN2 (P<0.05), PLIN3 (P<0.05), and PLIN5 (P<0.001) were closely related to the histological type of liposarcoma." (PMID 32368290, 2020). "PLIN2, PLIN3 and PLIN5 were widely expressed in liposarcomas, rhabdomyosarcomas, leiomyosarcomas, dermatofibrosarcoma protuberans, undifferentiated sarcomas, fibrosarcomas, Ewing's sarcomas and epithelioid sarcomas." (PMID 32368290, 2020).
oral squamous cell carcinoma (3 papers, 2022 to 2025). "Patients with oral squamous cell carcinoma at a late TNM stage exhibited higher levels of PLIN2 in immune cells and were susceptible to postoperative metastasis, indicating that LDs may regulate host immunity by affecting the function of immune cells." (PMID 38500157, 2024). "Elevated PLIN2 levels correlate with shorter OS, higher TNM stage, and poorer prognosis in patients with oral squamous cell carcinoma." (PMID 41223031, 2025). "This retrospective study included 96 oral squamous cell carcinoma (OSCC) samples and analyzed the spatial distribution of PLIN2 by immunohistochemistry (IHC) and LD level by oil red O staining." (PMID 35372038, 2022).